OTUD1 (OTU deubiquitinase 1)
Diseases named in the same sentence as OTUD1 in open-access papers (continued):
Sharing a sentence is not in itself a finding about the gene and the disease.
autoimmune disease (5 papers, 2023 to 2025). A disorder resulting from loss of function or tissue destruction of an organ or multiple organs, arising from humoral or cellular immune responses of the individual to their own tissue constituents. "Dysfunction of OTUD1 can contribute to excessive interferon production and thus autoimmunity; this is supported by the association of loss-of-function mutations in OTUD1 with autoimmune diseases (lupus erythematosus, rheumatoid arthritis or Hashimoto’s thyroiditis)." (PMID 39201568, 2024). "This indicates redundant regulation on additional levels but could also be understood as a sign of the sustained dysregulation of the immune system in favor of autoimmunity, as a loss of function in the OTUD1 gene was seen to be associated with autoimmune diseases." (PMID 39201568, 2024). "OTUD1 prevented excessive interferon production-induced autoimmune disease by removing K63-Ub on Lys98 of IRF3, thereby dampening IRF3 nuclear translocation and transcriptional activity, which blocked RIG-I-like receptor signaling." (PMID 40469292, 2025). "OTUD1 also participated in the coordination of intestinal immune responses and autoimmune diseases." (PMID 38012669, 2023). "In addition, there are OTUD1-related diseases, such as various cancers, autoimmune diseases, sepsis, inflammatory bowel disease, aGVHD, arteriosclerosis, and so on." (PMID 36829909, 2023). "Importantly, in addition to its association with various cancers, including multiple myeloma, OTUD1 is involved in acute graft-versus-host disease and autoimmune diseases such as systemic lupus erythematosus, rheumatoid arthritis, and ulcerative colitis." (PMID 36829909, 2023).
inflammatory bowel disease (5 papers, 2022 to 2025). A spectrum of small and large bowel inflammatory diseases of unknown etiology. "This study has demonstrated that OTUD1 is a central regulatory factor in these signal pathways, and the genetic ablation of OTUD1 is associated with inflammatory bowel disease, hepatitis, sepsis, and kidney cancer." (PMID 35941131, 2022). "Furthermore, OTUD1 is an important target for drug development for treating inflammatory bowel disease, hepatitis, sepsis, and kidney cancer due to its association between OTUD1 gene deletion and these disorders." (PMID 37695739, 2023). "Taken together, these findings indicate that OTUD1 is a suppressor of the NF-κB signaling pathway, and the aberrant OTUD1 activity induces inflammatory bowel diseases such as UC by the hyperactivation of the NF-κB pathway." (PMID 36829909, 2023). "In inflammatory bowel disease, the mucosa was found to express lower levels of OTUD1." (PMID 39201568, 2024).
ovarian tumor (5 papers, 2018 to 2024). "OTUD1, an ovarian tumor protease (OTU) family DUB, has an N-terminal-disordered alanine-, proline-, glycine-rich region (APGR), a catalytic OTU domain, and a ubiquitin-interacting motif (UIM)." (PMID 36829909, 2023). "By screening for key components in tumorigenesis and CSC maintenance in ovarian cancer, we identified the deubiquitinase OTUD1 as a unique factor and found that its high expression predicts poor prognosis and potentiates ovarian tumor cell stemness maintenance." (PMID 38351029, 2024). "OTUD1 belongs to the ovarian tumor (OTU) family of the deubiquitinases." (PMID 29734366, 2018). "Thus, Pearson correlation analysis between the expression level of B4GALT5 and OTU (ovarian tumour) family deubiquitinases (OTUB1, OTUB2, OTUD1, YOD1, OTUD3, OTUD4, OTUD7B) was performed." (PMID 36611197, 2023).
thyroid cancer (5 papers, 2017 to 2025). "OTUD1 was reported to be differentially expressed in thyroid cancer and to deubiquitinate and stabilize p5317,18." (PMID 29235476, 2017). "OTU domain-containing protein 1 (OTUD1) is involved in immune regulation related to infectious diseases and is a biomarker for thyroid cancer." (PMID 37695739, 2023).
cervical cancer (4 papers, 2019 to 2025). A primary or metastatic malignant neoplasm involving the cervix. "Previously, the DUBs OTUD1 and JOSD1 had been shown to regulate Mcl-1 expression in cervical cancer cells." (PMID 33627786, 2021). "Two other deubiquitinating enzyme, OTUD1 and JOSD1, have also been shown to regulate Mcl-1 in cervical cancer, suggesting that the regulation of Mcl-1 ubiquitination may be essential for cervical cancer progression." (PMID 40011575, 2025). "Furthermore, bioinformatics analysis data reveal that OTUD1 is a negative prognostic factor for liver cancer, ovarian cancer and specific subtypes of breast and cervical cancer." (PMID 31467488, 2019). "Thus, OTUD1 is a negative prognostic factor for liver cancer, ovarian cancer, specific subtypes of breast and cervical cancer." (PMID 31467488, 2019). "According to bioinformatics analysis, we found that OTUD1 is a negative prognostic factor for liver cancer and ovarian cancer and specific subtypes of breast and cervical cancer and that it could be considered as a therapeutic target for curing these cancers." (PMID 31467488, 2019).
esophageal squamous cell carcinoma (4 papers, 2021 to 2025). Esophageal squamous cell carcinoma (ESCC) is a type of esophageal carcinoma (EC) that can affect any part of the esophagus, but is usually located in the upper or middle third. "Low OTUD1 expression has been reported to be associated with chemoresistance and poor prognosis in esophageal squamous cell carcinoma (ESCC) patients, while wild-type OTUD1 xenografts inhibit ESCC growth and promote chemosensitivity." (PMID 41050073, 2025). "Recent data have demonstrated the central role of OTUD1 in activating caspase-independent and caspase-dependent apoptosis and that decreased OTUD1 expression contributes to promotion of chemoresistance in esophageal squamous cell carcinoma." (PMID 36182943, 2022). "Collectively, these results reveal the central role of OTUD1 in activating both caspase‐independent and caspase‐dependent apoptotic signaling and propose decreased OTUD1 expression as a key event promoting chemoresistance in esophageal squamous cell carcinoma." (PMID 33898171, 2021).
kidney cancer (4 papers, 2022 to 2024). Primary or metastatic malignant neoplasm involving the kidney. "Thus, we concluded that the orchestration of OTUD1 with KEAP1 functions to suppress kidney cancer in humans, and therefore, OTUD1 is a critical regulator to maintain homeostasis." (PMID 35941131, 2022). "Insight gleaned from the analysis of OTUD1 RNA‐seq data elucidates a potential nexus involving OTUD1 inhibition and the AKT and NF‐κB pathways in kidney cancer cells." (PMID 39011666, 2024). "The suppression of K63-ubiquitination of KEAP1 is mediated by OTU deubiquitinase 1 (OTUD1), which may inhibit ROS-induced oxeiptosis in kidney cancer cells." (PMID 39090114, 2024).
lung carcinoma (4 papers, 2017 to 2025). "Our previous study has demonstrated that the OTU family member, OTUD1, inhibited lung cancer progression." (PMID 40651961, 2025). "The tumor‐suppressive effect of OTUD1 highlights its potential as a therapeutic target to restrain lung cancer progression by preventing the spread and growth of malignant cells." (PMID 39678489, 2024). "In contrast, OTUD1 acts as a tumor suppressor in lung cancer." (PMID 39678489, 2024). "Consistently, lowered expression of OTUD1 has also been documented in lung cancer samples." (PMID 36182943, 2022).
ovarian carcinoma (4 papers, 2019 to 2024). A malignant neoplasm originating from the surface ovarian epithelium. "Consistently, we found that higher OTUD1 expression was significantly associated with low recurrence-free survival of liver and ovarian cancer patients by analysing the clinical data." (PMID 31467488, 2019). "High levels of OTUD1 are associated with poor prognosis in ovarian cancer patients." (PMID 38351029, 2024). "Herein, the multiomics screening reveal that OTUD1 protein plays an important role in retaining ovarian cancer stem cell (OCSC) properties." (PMID 38351029, 2024). "Here, the authors perform multi-omics and reveal that aggresome formation supports ovarian cancer stem cell properties via OTUD1 and ASK1/JNK signalling activation." (PMID 38351029, 2024). "Because ibrutinib is an FDA-approved drug with tolerable toxicity, we focused on the effect of ibrutinib on the tumorigenicity of OTUD1-high ovarian cancer cells." (PMID 38351029, 2024). "To verify our hypothesis, we knocked out OTUD1 in the ovarian cancer cell lines SKOV3, OVCAR8 and CAOV3 by using two distinct sgRNAs." (PMID 38351029, 2024). "Taken together, these results strongly suggest that OTUD1 may act as a proto-oncogene in ovarian cancer and potentiate OSCS maintenance." (PMID 38351029, 2024). "However, the roles of OTUD1 in liver and ovarian cancer are still needed further investigation by using xenograft tumour model, cancer metastasis animal model, and other in vivo cancer models." (PMID 31467488, 2019). "Therefore, OTUD1 is a potential target for liver and ovarian cancer therapy." (PMID 31467488, 2019). "ASK1/JNK inhibitors very effectively suppressed OSCS induced by OTUD1 overexpression, and ibrutinib, an FDA-approved MKK7 inhibitor, preferentially reduced the tumorigenicity of OTUD1high ovarian cancer cells." (PMID 38351029, 2024). "To further verify the effect of ibrutinib, we selected several ovarian cancer cell lines, and SKOV3 cells were shown to contain a relatively higher protein abundance of OTUD1 than OVCAR3 cells, accompanied by elevated protein levels of ASK1, p-ASK1, p-JNK and p-c-Jun." (PMID 38351029, 2024). "Notably, the disruption of OTUD1-based aggresomes or treatment with ASK1/JNK inhibitors, including ibrutinib, an FDA-approved drug that was recently identified as an MKK7 inhibitor, effectively reduced OCSC stemness (OSCS) of OTUD1high ovarian cancer cells." (PMID 38351029, 2024). "OTUD1 is also a negative prognostic factor for ovarian cancer patients." (PMID 31467488, 2019).
Sepsis (4 papers, 2022 to 2025). Sepsis is defined as life-threatening organ dysfunction caused by a dysregulated host response to infection. "Consistent with the mRNA level changes observed in scRNA-seq, western blot showed that OTUD1 protein level was up-regulated during sepsis, suggesting that elevated OTUD1 expression was associated with SAE." (PMID 40500776, 2025). "To further clarify the pathophysiological role of OTUD1 in vivo, we adopted LPS/GalN-induced acute hepatitis and LPS-induced sepsis models, which are associated with inflammatory and oxidative responses." (PMID 35941131, 2022). "Collectively, these clinical and bioinformatic findings implicate OTUD1 as a critical regulator of neuroinflammation in sepsis pathophysiology, potentially mediated through microglial pyroptosis-dependent mechanisms." (PMID 40500776, 2025). "To elucidate the clinical relevance of OTUD1 in sepsis and SAE, we interrogated publicly available sepsis datasets." (PMID 40500776, 2025). "The results demonstrated that sepsis patients with lower OTUD1 expression exhibited a decreased 28-day mortality rate (53% vs. 47%)." (PMID 40500776, 2025). "Comparative analysis revealed significantly elevated OTUD1 expression levels in sepsis patients compared to healthy controls (GSE154918)." (PMID 40500776, 2025). "Clinical data also indicated that OTUD1 expression is obviously increased in sepsis patients, and higher levels of OTUD1 are highly correlated with neuroinflammation and 28-day mortality." (PMID 40500776, 2025). "Furthermore, Gene set enrichment analysis (GSEA) revealed that high OTUD1 expression was positively correlated with Neuroinflammation and Glutamatergic Signaling in sepsis patient, suggesting a potential link between OTUD1 and neurological dysregulation in sepsis." (PMID 40500776, 2025).
gastric cancer (3 papers, 2021 to 2024). A primary or metastatic malignant neoplasm involving the stomach. "OTUD1 boosts gastric cancer aggressiveness by deubiquitinating the EBV protein BALF1." (PMID 39605891, 2024). "Effective blockade of STAT3 activity by the STAT3 inhibitor stattic sensitized gastric cancer cells to cisplatin and reduced expression of the cisplatin resistance‐related genes G3BP2, THOC1, ATP7A, and OTUD1." (PMID 34375503, 2021). "Effective blockade of the STAT3 activity by STAT3 inhibitor sensitized gastric cancer cells to cisplatin and reduced the cisplatin‐resistant‐related gene G3BP2, THOC1, ATP7A, and OTUD1 expression." (PMID 34375503, 2021). "In gastric cancer (GC), DUBs like USP20, OTUB1, and OTUD1 play significant roles." (PMID 39678489, 2024).
heart failure (3 papers, 2023 to 2025). Inability of the heart to pump blood at an adequate rate to meet tissue metabolic requirements. "The first study demonstrated that OTUD1 promotes pathological cardiac remodeling and heart failure by targeting STAT3 in cardiomyocytes." (PMID 39309432, 2024). "In this study, we found OTUD1 upregulation in heart failure samples from patients at the single-cell level." (PMID 39309432, 2024). "The second study (doi: 10.1016/j.bbadis.2024.167018) investigated the involvement of OTUD1 in heart failure induced by isoprenaline and myocardial infarction, identifying PDE5A as a critical target." (PMID 39309432, 2024). "Our analyses confirmed that OTUD1 was predominantly detected in cardiomyocytes, with heart failure samples demonstrating significantly higher levels of OTUD1 expression compared to control samples." (PMID 39309432, 2024). "First, OTUD1 upregulation in human heart failure samples was detected from public single-cell sequencing data rather than clinically acquired data." (PMID 39309432, 2024). "In the GSE57338 dataset (one heart failure dataset), both OTUD1 and TNFAIP3 were upregulated." (PMID 39309432, 2024). "Compared with the non-hypertrophic myocardium tissues, the mRNA level of OTUD1 was up-regulated in hypertrophic myocardium tissues of heart failure patients." (PMID 37153745, 2023).
metastatic tumors (3 papers, 2017 to 2024). "Upregulation of OTU deubiquitinase 1 (OTUD1) stabilizes FGL1 through deubiquitination, further influencing the immune escape of metastatic tumors via the FGL1-LAG-3 axis." (PMID 38816776, 2024). "But for the patients without lymph node signal, OTUD1 failed to distinguish prognosis, suggesting a more significant role of OTUD1 in antagonizing metastatic tumors." (PMID 29235476, 2017). "However, knockdown of either OTUD1 or FGL1 in MC38 cells reduced hepatic metastases, which could be rescued by overexpressing rFGL1, indicating the critical role of FGL1 in TNFα-mediated progression of metastatic tumors." (PMID 37872170, 2023).
non-small cell lung carcinoma (3 papers, 2022 to 2023). A group of at least three distinct histological types of lung cancer, including non-small cell squamous cell carcinoma, adenocarcinoma, and large cell carcinoma. "High expression levels of OTUD1 were associated with improved prognosis in non-small cell lung cancer and adenocarcinoma." (PMID 36497496, 2022). "For example, high mRNA expression levels of OTUD1, OTUD3, OTUD4, and ALG13 are associated with improved prognosis in non-small cell lung cancer (NSCLC) and adenocarcinoma, but not in squamous cell carcinoma." (PMID 36829909, 2023).
periodontitis (3 papers, 2023 to 2025). An acute or chronic inflammatory process that affects the tissues that surround and support the teeth. "Reciprocally, loss of OTUD1 enhances neutrophil secretion and increases susceptibility to periodontitis." (PMID 37639212, 2023). "Conversely, depletion of OTUD1 increases the susceptibility to periodontitis through augmenting the transport of proinflammatory cytokines and adhesive proteins on neutrophil." (PMID 37639212, 2023). "Our data thus indicate that loss of OTUD1 promotes the development of neutrophil with secretory phenotype during periodontitis." (PMID 37639212, 2023). "Conversely, deletion of OTUD1 increases the susceptibility of mice to experimental periodontitis and exacerbates tissue damage." (PMID 37639212, 2023). "Collectively, our data demonstrate that loss of inflammation‐responsive OTUD1 increases the susceptibility of mice to periodontitis." (PMID 37639212, 2023). "Clinical investigations further revealed a notable increase in both the mRNA and protein levels of OTUD1 in the gingival tissues of patients with periodontitis compared to healthy controls." (PMID 39626954, 2025). "OTU domain-containing protein 1 (OTUD1) expression has been linked to decreased inflammatory secretion, and its depletion has been associated with severe periodontitis." (PMID 40290655, 2025). "Subsequent flow cytometry assay confirmed that loss of OTUD1 facilitated CD9 and CD47 surface expression in neutrophils during periodontitis and peritonitis." (PMID 37639212, 2023). "Both transcription level and protein level were remarkably increased in patients gingival tissues and gingival neutrophils with periodontal inflammation, supporting the notion that OTUD1 is upregulated during the pathogenesis of periodontitis." (PMID 37639212, 2023). "In human and mouse periodontitis, the waning of inflammation is correlated with OTUD1 upregulation, whereas severe periodontitis is induced when neutrophil‐intrinsic OTUD1 is depleted." (PMID 37639212, 2023). "Here, we report that deubiquitinase OTUD1 is selectively expressed in gingival neutrophils and upregulated during periodontitis." (PMID 37639212, 2023). "To further investigate the biological role of OTUD1 during the process of periodontitis, we utilized Otud1−/− or WT mice and induced experimental periodontitis by ligature placement and Porphyromonas gingivalis (P. gingivalis) infection." (PMID 37639212, 2023). "The biological function of OTUD1 in tissue remodeling and adaptive immune response during chronic periodontitis thereby needs further investigation." (PMID 37639212, 2023). "Further analysis reveals that OTUD1 is mainly expressed by gingival neutrophils and selectively upregulated during periodontitis." (PMID 37639212, 2023). "To study the mechanism by which deletion of OTUD1 exacerbates periodontitis, we performed a series of assays including flow cytometry, quantitative real‐time PCR, immunohistochemistry and routine blood test to assess the status of neutrophils during periodontitis." (PMID 37639212, 2023). "We next experimentally assessed the status of OTUD1 during periodontitis." (PMID 37639212, 2023). "Our findings thus shed new light on an unexplored mechanism of neutrophil‐mediated periodontitis, implying that OTUD1 or protein transport signaling may be a potential target for periodontitis treatment." (PMID 37639212, 2023). "Together, these findings thus reinforce the critical role of secretory neutrophils in periodontitis and OTUD1 might be involved in modulation of periodontal immune response." (PMID 37639212, 2023). "Meanwhile, DUBs, including OTUD1, A20, CYLD, UCH‐L1 and USPs, also broadly modulate periodontitis progression by regulating signalling pathways such as NF‐κB, Wnt/β‐catenin, NLRP3, and BMP2." (PMID 39626954, 2025).
renal clear cell carcinoma (3 papers, 2022 to 2025). "We found that low levels of OTUD1 expression are significantly associated with a poor prognosis in renal clear cell carcinoma patients." (PMID 35941131, 2022). "In addition, OTUD1 was also significantly under-expressed in renal clear cell carcinoma (ccRCC) tissues, and low OTUD1 expression was associated with shorter disease-free survival and poor prognostic factors for overall survival (OS) in ccRCC patients." (PMID 41050073, 2025).